GSDMB (gasdermin B)
Diseases named in the same sentence as GSDMB in open-access papers (continued):
Sharing a sentence is not in itself a finding about the gene and the disease.
gastric cancer (21 papers, 2014 to 2025). A primary or metastatic malignant neoplasm involving the stomach. "Significant GSDMB amplification is present in Her2‐positive gastric cancer; although its mutation load is low, this patient population may also benefit from immunotherapy, which has been substantiated by the KEYNOTE‐811 study." (PMID 37587833, 2023). "The upregulation of GSDMB in HER2-positive gastric cancer cells provides a theoretical basis for the efficacy of IBI315, suggesting the potential application of GSDMB in gastric cancer immunotherapy." (PMID 40452932, 2025). "In gastric cancer, particularly in HER2-positive gastric cancer, GSDMB plays a crucial role in pyroptosis." (PMID 40452932, 2025). "Our research found that 66% of Her2‐positive gastric cancers in the TCGA database harbored GSDMB amplifications." (PMID 37587833, 2023). "Remarkably, an upregulation of GSDMB expression was observed in Her2‐positive gastric cancer cells, thereby substantiating the basis for the effectiveness of IBI315." (PMID 37587833, 2023). "The Cancer Genome Atlas (TCGA) database screenings showed that GSDMB, ‐D, and ‐E were expressed in gastric cancers." (PMID 37587833, 2023). "GSDMB is frequently co-expressed with HER2/Erbb2 oncogene in breast and gastric carcinomas, where GSDMB over-expression promotes tumorigenesis, invasion, metastasis, and resistance to therapy." (PMID 36899106, 2023). "Based on several studies, hyperexpression of GSDMB in hepatocellular carcinoma, gastric cancer, and cervical cancer was considered as an oncogene that would appear to be involved in cancer invasion and metastasis." (PMID 35847844, 2022). "It has been reported that while GSDMA is silenced in gastric cancer, GSDMB is overexpressed in several types of cancers (e.g., breast and gastric cancers)." (PMID 36003332, 2022). "In HER2 gastric carcinomas, alike HER2 breast tumors, GSDMB over-expression associates with relapse (p = 0.060), thus supporting the relationship between high levels of GSDMB and poor prognosis in gastric tumors." (PMID 36163066, 2022). "In tumors, GSDMB is frequently over-expressed in breast, liver, colon, cervical and gastric carcinomas, and GSDMB upregulation can promote multiple pro-tumor functions." (PMID 36163066, 2022). "Several studies on solid cancers have verified that GSDMB is extremely expressed in cancer tissues including uterine, cervical, breast, and stomachic cancers." (PMID 34804944, 2021). "Additionally, the long terminal repeat promoter drives GSDMB expression in gastric cancer specimens." (PMID 40721578, 2025). "In addition, GSDMA was identified as a tumor suppressor gene in gastric cancer, whereas GSDMB was observed to be overexpressed and exhibited oncogenic properties." (PMID 37950289, 2023). "Notably, GSDMB is found to be elevated in Her2‐positive gastric cancer cells, providing a rationale for IBI315's efficacy." (PMID 37587833, 2023). "Interestingly, we found that the expression of GSDMB increased when gastric cancer cells were treated with IFNγ, consistent with Shao and co‐workers findings." (PMID 37587833, 2023). "Therefore, to evaluate further the functional role of GSDMB in gastric cancer requires future studies expressing each of the isoforms under the recently described stomach-specific gene promoters." (PMID 35281099, 2022). "Finally, we validated these results in clinical samples where GSDMB/Rab7/LC3B co-expression associates significantly with relapse in HER2 breast and gastric cancers." (PMID 36163066, 2022). "Our data together with previous reports in gastric cancer indicate that GSDMB isoforms have differential expression levels within tumors and in normal tissues, and importantly, they may have distinct cellular localization and biological functions." (PMID 24675552, 2014).
gastric cancer (continued). "The comparative analysis of these proteins suggests that GSDMA may act as tumor suppressor gene in gastric cancer, while GSDMB could be considered as an oncogene based on its amplification and over-expression in this cancer type." (PMID 24675552, 2014). "In gastric cancer, pyroptosis-related genes such as GSDMA, GSDMB, and GSDMC were revealed to be abnormally expressed in GC and associated with tumor progression." (PMID 35198013, 2022). "Additionally, GSDMB is expressed in all examined cases of esophageal and gastric cancers." (PMID 34858408, 2021). "Additionally, GSDMA expression was frequently suppressed in esophageal cancer cell lines and gastric cancer cell lines, whereas GSDMB was expressed in all investigated cancer cell lines and also showed evidence of gene amplification and overexpression in some cases of gastric cancer." (PMID 26484354, 2015). "Moreover, GSDMB gene amplification has been reported in a small subset of gastric carcinomas." (PMID 24675552, 2014). "Elevated GSDMB in Her2‐positive gastric cancer cells supports IBI315's efficacy, highlighting its potential for refractory Her2‐positive gastric cancer immunotherapy." (PMID 37587833, 2023). "While screening gastric cancer cell lines, PDX‐1 and PDXO‐1, we focused on GSDMB, and in subsequent knockdown experiments, we confirmed that the pyroptosis and antitumor effects of IBI315‐mediated T cells were dependent on GSDMB." (PMID 37587833, 2023). "Four, and most notably, the GSDMB/Rab7 and GSDMB/LC3B puncta positive co-expression significantly correlated with relapse in HER2/GSDMB + breast and gastric carcinomas." (PMID 36163066, 2022). "Also, some individual pyroptosis genes have been studied, such as NOD2 in colorectal cancer, gasdermin B (GSDMB) in digestive system, and Gasdermin D (GSDMD) in gastric cancer." (PMID 36249755, 2022). "In addition to GSDMA, GSDMB, and GSDMC, GSDMD reportedly inhibited proliferation of the gastric cancer cell line MKN28 in a colony formation assay." (PMID 34858408, 2021). "Other studies demonstrated that the expression levels of GSDMB and Alu versus long-terminal region- (LTR-) derived promoter utilization could be valuable markers in assessing the growth and development of gastric cancer." (PMID 34957313, 2021). "In gastric cancer, GSDMB is highly expressed in most cancerous tissue samples but not in most normal gastric samples, and may be associated with increased levels of invasion." (PMID 35990696, 2022).
childhood asthma (15 papers, 2009 to 2025). "Relatively, many previous genome-wide association studies show that there is an association between the Gasdermin A and Gasdermin B polymorphisms and susceptibility to adult and childhood asthma in different populations, including the Jordanian population." (PMID 36201519, 2022). "Orosomucoid 1-like 3 (ORMDL3) and gasdermin B (GSDMB) polymorphisms were associated with childhood asthma." (PMID 30906771, 2019). "The TT-genotype of ADAM33 rs511898 (p = 0.03), the CG/GG-genotype of ADAM33 rs528557 (p = 0.08) and the TT-genotype of ORMDL3/GSDMB rs7216389 (p = 0.08) were negatively associated with childhood asthma." (PMID 25768087, 2015). "Notably, miR-15a was highly associated with the regulation of the GSDMB gene, which resides on the chromosome 17q locus that has become the most replicated childhood asthma association in previously published GWAS." (PMID 33291534, 2020). "This study examines the association between the gasdermin B (GSDMB) gene variant rs7216389 and childhood asthma, with a focus on gender-based differences, environmental factors, and lung function measurements in affected children." (PMID 39906448, 2025). "Previous studies have reported that the 17q21 locus alleles in genes GSDMA, GSDMB, IKZF3, ZPBP2, and ORMDL3 are associated with increased risk and severity of childhood asthma and increased number of early wheezing illnesses." (PMID 36967681, 2023). "Five genes were found to be associated with self-reported childhood asthma in COPDGene: IL1RL1, IL13, LINC01149, near GSDMB, and in the C11orf30-LRRC32 region." (PMID 30373671, 2018). "Prior GWAS have implicated genetic susceptibility specific to childhood asthma, including variants in ORMDL3/GSDMB, IL1RL1, IL33, and RAD50." (PMID 30373671, 2018). "Our GWAS dataset supported an association between identical SNPs reported in ORMDL3/GSDMB/GSDMA, IL5/RAD50/IL13, HLA-DR/DQ, and SMAD3 and pediatric asthma (P<0.05)." (PMID 21814517, 2011). "In this latest study, genes such as ORMDL3 and GSDMB expectedly showed the strongest significance to childhood asthma (random-effect P values of 5.24 × 10-21 and 6.45 × 10-23 respectively)." (PMID 22188591, 2011). "The last gene on our list, GSDMB, is also a recognized gene for childhood asthma." (PMID 40133993, 2025). "Variations in the ORMDL3/GSDMB locus, and GSDMB, CD14, CC16, CYSLTR1, ST2, GSTP1, and IL1RL1 genes among others, some of which may be epithelium and innate immunity specific have also been shown to be associated with childhood onset asthma." (PMID 34912343, 2021). "In the ADEM study, the minor alleles of ADAM33 rs511898 and rs528557 and the ORMDL3/GSDMB rs7216389 polymorphisms were negatively associated, whereas the minor alleles of IL4 rs2243250 and rs2070874 polymorphisms were positively associated with childhood asthma." (PMID 25768087, 2015). "In a genome-wide association study, it was reported that 17q21 loci which include ORMDL3/GSDMB genes is highly correlated with childhood asthma, but unlike our results, GSDMB is not correlated to total IgE serum levels." (PMID 36201519, 2022).
cervical cancer (14 papers, 2014 to 2025). A primary or metastatic malignant neoplasm involving the cervix. "GSDMB overexpression in various cancers, including hepatocellular carcinoma, gastric, breast, and cervix cancers has been mainly associated with tumor progression." (PMID 40783818, 2025). "Although it is an attractive candidate for cervical cancer risk, experimental evidence for GSDMB as the causal gene underlying the signal on 17q12 is still lacking." (PMID 34680286, 2021). "Interestingly, higher levels of Gasdermin B (also known as Gasdermin-like, GSDML) had previously been associated with tumour progression in cervical cancer." (PMID 34680286, 2021). "According to previous research on human malignancies, GSDMB is upregulated in tumour tissues, including breast, uterine, gastric, and cervical cancers." (PMID 36163033, 2022). "Consistently, GSDMB is significantly more upregulated in in uterine cervix cancer tissues compared with other precancerous tissues." (PMID 34858408, 2021). "Gasdermin B expression has been detected in some tumor types such as hepatocarcinomas, gastric and cervix cancers; and its over-expression has been related to tumor progression." (PMID 24675552, 2014). "Nonetheless, GSDMB-1 has also been described to show nuclear localization in cervix carcinomas." (PMID 24675552, 2014). "Here, we review cervical cancer susceptibility variants arising from recent genome-wide association studies and meta-analysis in large cohorts and propose 2q14 (PAX8), 17q12 (GSDMB), and 5p15.33 (CLPTM1L) as consistently replicated non-HLA cervical cancer susceptibility loci." (PMID 34680286, 2021).
autoimmune disease (13 papers, 2013 to 2025). A disorder resulting from loss of function or tissue destruction of an organ or multiple organs, arising from humoral or cellular immune responses of the individual to their own tissue constituents. "The encoded protein Gasdermin-B mediates pyroptosis and, in addition to MS, genetic variants in the GSDMB gene have also been associated with susceptibility to other multifactorial autoimmune diseases like rheumatoid arthritis and ulcerative colitis." (PMID 36405756, 2022). "IRF8, TMEM39A and IKZF3-ZPBP2 were previously identified as susceptibility loci for SLE in the multiracial replication study, Besides, ORMDL3 and GSDMB were found to have susceptibility loci for autoimmune diseases." (PMID 28427360, 2017). "These include disease-associated variants (e.g., an eQTL for SLC22A5 associated with Crohn’s disease and a sQTL for GSDMB associated with a range of autoimmune diseases)." (PMID 27863252, 2016). "Additionally, several studies found genetic variants in orosomucoid like 3 (ORMDL3) and gasdermin B (GSDMB) were associated with the risk of autoimmune disease." (PMID 28427360, 2017).
allergic disease (8 papers, 2013 to 2023). An immune response that occurs following re-exposure to an innocuous antigen, and that requires the presence of existing antibodies against that antigen. "The HWE equilibrium law was followed by the frequency distributions of the following polymorphisms in allergy patients: CYSLTR1 rs320995, GSDMB rs7216389, GPIIIa rs5918, GP1BA rs6065, PEAR1 rs12041331, PAI-1 rs1799762, and TNF-α rs1800629 (p > .05)." (PMID 36911417, 2023). "In addition to the “allergic disease genes”, there are “tissue-specific genes” that contribute to the expression to a certain atopic disease, such as GSDMB locus, where none of association was detected in the present study, exerting greatest effect in bronchi tissues." (PMID 32082391, 2020). "The expression of GSDMB in the thymus and CD8+ and CD4+ T-cells would increase the plausibility of this inference, especially given the involvement of type 1 and type 2 immune responses in autoimmune and allergic disease respectively." (PMID 24044605, 2013).
Crohn disease (8 papers, 2015 to 2026). A gastrointestinal disorder characterized by chronic inflammation involving all layers of the intestinal wall, noncaseating granulomas affecting the intestinal wall and regional lymph nodes, and transmural fibrosis. "GSDMB showed predominantly protective effects: increased expression in multiple T‐cell subsets associated with lower risk of UC, Crohn disease, rheumatoid arthritis, and ankylosing spondylitis, but showed an opposite liability in primary sclerosing cholangitis." (PMID 41442179, 2026). "However, another study pointed out that upregulated GSDMB in patients with sepsis and Crohn’s disease promoted caspase-4 activity and GSDMD cleavage, revealing a GSDMB-regulated novel regulatory mechanism for GSDMD-induced pyroptosis in inflammatory diseases." (PMID 34858408, 2021).
glioma (7 papers, 2021 to 2023). A benign or malignant brain and spinal cord tumor that arises from glial cells (astrocytes, oligodendrocytes, ependymal cells). "Three genes (NLRP2, NLRP9, and GSDMB) were downregulated, while the remaining 54 genes were upregulated in the glioma group." (PMID 35547808, 2022). "Moreover, ten pyroptosis‐related regulators were upregulated in glioma samples compared to normal brain tissues, with exception of GSDMB." (PMID 36161280, 2023). "CASP1 displayed the highest mutation frequency, followed by Gasdermin C (GSDMC), while CASP3, Gasdermin B (GSDMB), Gasdermin E (GSDME), and GZAMB did not display any mutations in glioma samples." (PMID 35620284, 2022). "Although GSDMA, GSDMB, and GSDME expression was not significantly correlated with glioma prognosis, it had significantly different levels in different clinical or molecular subtypes, suggesting that their potential value in glioma remains to be investigated." (PMID 35784306, 2022). "While the trends of GSDMB, GSMDC and DFNB59 expression in glioma were not consistent across four datasets." (PMID 34830775, 2021).
gastric tumor (6 papers, 2014 to 2022). "Second, strong Rab7 or LC3B puncta was significantly more frequent in GSDMB over-expressing breast and in gastric tumors." (PMID 36163066, 2022). "A potential GSDMB-mediated immune rejection of gastric tumor cells is unlikely in our model since GSDMB2 is expressed in diverse cell types, including the immunocytes." (PMID 35281099, 2022). "Indeed, in MCF7 cells, both GSDMB isoforms are mainly detected in the cytoplasm, consistent with the cytoplasmic distribution of the endogenous GSDMB detected in HCC1954 cells and similar to the previously reported localization in hepatocellular carcinomas and gastric tumors." (PMID 24675552, 2014).
colon cancer (5 papers, 2021 to 2024). "Conversely, GSDMB has been identified as playing a pivotal role in the metastasis of colon cancer cells to distant organs by modulating cell adhesion and migration processes." (PMID 39030523, 2024). "Our research sheds light on the clinical implications and functional roles of CD8+T cells expressing GZMA and IFN-γ, as well as colon cancer cells expressing GSDMB." (PMID 39030523, 2024). "In summary, it is crucial to further explore how CD8+TILs co-expressing GZMA and IFN-γ regulate GSDMB in colon cancer epithelial cells and their impact on patient prognosis." (PMID 39030523, 2024). "We found that higher frequency of GSDMB+CK+ cells was observed in colon cancer tissues compared with normal colon tissues (P < 0.001)." (PMID 39030523, 2024). "In this study, we utilized mIHC to examine the spatial distribution and clinical significance of GZMA, IFN-γ, and GSDMB within TME of human colon cancer patients." (PMID 39030523, 2024). "Our findings revealed a pronounced expression of GSDMB in colon cancer cells, with GZMA and IFN-γ frequently co-expressed within CD8+TILs." (PMID 39030523, 2024). "To verify the impact of epithelial cell expressed GSDMB on patients with colon cancer, we calculated the proportion of GSDMB+CK+ cells and evaluated the prognostic value of GSDMB+CK+ cells in human colon cancer tissues." (PMID 39030523, 2024). "This underscores the multifaceted role of GSDMB+CK+ cells in the pathogenesis of colon cancer." (PMID 39030523, 2024). "Moreover, investigating the effects of GZMA+IFN-γ+CD8+TILs and GSDMB+ tumor epithelial cells on signaling pathways within the colon cancer TME is essential." (PMID 39030523, 2024). "However, the interaction between GZMA-expressing CD8+T cells and GSDMB-expressing tumor cells in colon cancer remains poorly understood." (PMID 39030523, 2024). "However, a positive correlation was detected between the number of GZMA+IFN-γ+CD8+TILs and GSDMB+CK+ cells within the colon cancer microenvironment (r = 0.221, P = 0.033)." (PMID 39030523, 2024). "Although no statistical correlation was observed between the infiltration ratio of GSDMB+CK+ cells and patients’ prognosis in colon cancer, these cells exhibit enhanced immunogenic properties, contributing to antigen processing, presentation, and intercellular adhesion." (PMID 39030523, 2024). "Moreover, it is imperative for future studies to unravel the precise mechanisms by which GZMA+IFN-γ+CD8+TILs target GSDMB-expressing colon cancer cells and facilitating pyroptosis." (PMID 39030523, 2024). "In related studies of tumor cells, GSDMB was found to be highly expressed in breast, gastric, liver, cervical, and colon cancers; therefore, some scholars believe that GSDMB may be involved in cancer progression and metastasis as an oncogene." (PMID 36569221, 2022). "mIHC staining results revealed that the elevated frequencies of CK+ and GSDMB+ cells were detected in colon cancer tissues relative to normal colon tissues (P < 0.001)." (PMID 39030523, 2024).
rheumatoid arthritis (5 papers, 2019 to 2026). A chronic, systemic autoimmune disorder characterized by inflammation in the synovial membranes and articular surfaces. "Small case–control cohorts and eQTL screens have linked GSDMB variants or reduced expression to rheumatoid arthritis susceptibility, and a Han‐Chinese study reported GSDMB SNPs that modulate ankylosing spondylitis severity." (PMID 41442179, 2026).
Sepsis (5 papers, 2021 to 2024). Sepsis is defined as life-threatening organ dysfunction caused by a dysregulated host response to infection. "Among them, four classes are implicated in sepsis, including GSDMA, GSDMB, GSDMD and GSDME, with GSDMD being the most widely studied." (PMID 38022612, 2023). "GSDMB can also contribute to the development of sepsis by activating GSDMD." (PMID 38022612, 2023). "Apoptotic caspase-7 cleaved GSDMB (a potential proinflammatory mediator in sepsis) to block non-canonical pyroptosis to avoid over-inflammation in sepsis." (PMID 39040114, 2024).